LGALS3 (galectin 3)
Diseases named in the same sentence as LGALS3 in open-access papers (continued):
Sharing a sentence is not in itself a finding about the gene and the disease.
cancer (continued). "Galectin-3, a β-galactoside-binding lectin, plays a key role in several cellular pathways involved in chronic inflammation, heart disease and cancer." (PMID 36914828, 2023). "Numerous studies have considered galectin-3 or Glycogen synthase kinase 3 beta (GSK3B) as a potential prognosis marker for various cancers." (PMID 37185758, 2023). "Binding of galectin-3 to TF/MUC1 on cancer cells also increases cancer cell-cell homotypic aggregation and survival in the blood circulation." (PMID 37612278, 2023). "Galectin-3 is now well recognized as a multi-functional promoter of cancer progression and metastasis." (PMID 37055381, 2023). "Higher levels of circulating galectin-3 are seen in cancer patients, in particularly those with metastases." (PMID 37055381, 2023). "Overall, this study suggests an important mechanism in galectin-3-mediated promotion of cancer progression." (PMID 37055381, 2023). "It provides further evidence to the increased realization of galectin-3 as a potential therapeutic target for the treatment of cancer." (PMID 37055381, 2023). "It provides further evidence to the increased realization of galectin-3 as a potential therapeutic target for cancer treatment." (PMID 37055381, 2023). "Galectin-3 in cancer patients induces secretion of IL-6, G-CSF, sICAM-1 and GM-CSF from blood vascular endothelial cells in vitro and in mice." (PMID 38144531, 2023). "Galectin-3 (Gal-3) is a β-galactoside-binding lectin expressed in various types of cancers and plays a vital role in PitNET cell proliferation." (PMID 37958702, 2023). "Different molecules such as EGFR, PTEN, V-ATPase, syndecan 1 and galectin-3 play distinct roles in the metabolic regulation of RAS-mediated macropinocytosis in cancer." (PMID 37535087, 2023). "The relationships between MUC1 mucin with T antigen and galectin-3 seem to be very important in cancer development." (PMID 37345016, 2023). "Knockdown of galectins using ASOs has been extensively used to demonstrate the role of galectin-1 and galectin-3 in cancer." (PMID 37753083, 2023). "We found a similar positive correlation between LGALS3 and cancer-specific EMT signature scores in OVCA420 cells treated with either EGF (R2 = 0.01) or TNF-α (R2 = 0.02)." (PMID 38086828, 2023). "Galectin-3 (Gal-3), a beta-galactoside-binding lectin, plays a pivotal role in various cellular processes, including immune responses, inflammation, and cancer progression." (PMID 37298569, 2023). "Many cell surface glycoproteins such as growth factor receptors, adhesion and signalling proteins are known to be recognized by galectin-3 and are differentially expressed by different cancer types." (PMID 37055381, 2023). "Using cancer cell membranes to fabricate drug-targeting delivery systems makes cancer cell membranes carry NPs to target cancer tissues via Thomsen–Friedenreich antigen-galectin-3 interactions." (PMID 36839943, 2023). "Galectin-3 interacts with TF-antigen on the surface of the transmembrane mucin protein MUC-1 in cancer cells." (PMID 36873388, 2023). "Galectin-3 can also bind to hnRNP L to stabilize the mucin MUC4 mRNA in the cytoplasm of cancer cells." (PMID 36823664, 2023). "Positive correlations between fecal galectin-3 concentrations and the cancer biomarkers alpha-fetoprotein and carcinoembryonic antigen were also observed." (PMID 37189804, 2023). "Galectin-3 expression in PC3 human cancer cells resulted in cell cycle arrest at the G1 phase; upregulation of p21 levels in nuclei, and hypophosphorylation of the tumor suppressor protein pRb." (PMID 36873388, 2023). "Non-invasive biomarkers to monitor the therapeutic success of cancer therapy are of clinical value, and urinary galectin-3 is an interesting protein in this regard." (PMID 37189804, 2023).
cancer (continued). "It was revealed that increased expression of the T antigen has a big impact on promoting cancer progression and metastasis, among others, due to the interaction of this antigen with the β-galactose binding protein galectin-3 (Gal-3)." (PMID 37345016, 2023). "T antigen is crucial in the adhesion of many different cancer cells to the endothelium through interaction with galectin-3, and in this way, promotes metastasis." (PMID 37685842, 2023). "In this study, the secretion of several proteases including cathepsin-B, MMP-1 and MMP-13 by cancer cells was shown to be significantly increased in response to the presence of galectin-3." (PMID 37055381, 2023). "MUC1 mucin with T antigen and galectin-3 with high affinity to T disaccharide are both overexpressed in a variety of human cancers." (PMID 37345016, 2023). "LGALS3 has been considered as one of the promising targets for cancer immunotherapy, and LGALS3 inhibitors can inhibit T cell proliferation and activation through ligand combinations." (PMID 37853322, 2023). "This study thus reveals an important mechanism in galectin-3-mediated promotion of cancer progression and metastasis." (PMID 37055381, 2023). "Recently, some reports have identified a correlation between galectin-3 and β-catenin expression in several cancers." (PMID 37185758, 2023). "LCP contains abundant galactans, which are believed to antagonize galectin-3 (GAL-3), a pro-metastatic protein that has a critical role in the cancer cell profile." (PMID 37514364, 2023). "Galectin-3 has a molecular weight of 31 kDa, and it was first identified in immune cells and subsequently found in a series of normal and cancer cells." (PMID 37491623, 2023). "Further studies are needed to detail the actions of galectin-3 on liver stromal cells in addition to cancer cells during the establishment of the inflammatory liver metastatic niche." (PMID 38052804, 2023). "Given that fibrosis is a well-established pathophysiological consequence of many cancer therapies and promising preclinical studies, there was initially enthusiasm for galectin-3 as a biomarker of cancer therapy-induced cardiotoxicity." (PMID 37796395, 2023). "Changes in the expression of the Galectin-3 are commonly seen in cancer and pre-cancerous conditions." (PMID 36936148, 2023). "Overall results implicate that galectin-3 is a pro-metastatic factor that mediates interactions between cancer cells and hepatocytes in liver metastatic lesions." (PMID 38052804, 2023). "Many studies have shown that overexpression of galectin-3 promotes multiple steps in cancer progression and metastasis such as cancer cell adhesion, invasion, angiogenesis and immune suppression." (PMID 37055381, 2023). "Galectin-3 (Gal-3) is a protein involved in cancer cell proliferation, apoptosis, and metastasis and represents a promising target for cancer therapy." (PMID 37631339, 2023). "Galectin-3 is required for efficient uptake and infection of minute virus of mice, and viral infectivity is positively correlated with galectin-3 expression in human cancer cell lines." (PMID 36823664, 2023). "The appearance of the cancer-associated carbohydrate T antigen on MUC1 mucin overexpressed in cancer cells, and the increased expression of galectin-3 are both typical features in various cancers." (PMID 37345016, 2023). "Galectin-3 (Gal3) is one of the most studied members of the galectin family that mediate various biological processes such as growth regulation, immune function, cancer metastasis, and apoptosis." (PMID 37175823, 2023). "With regard to the potential limitations of established cardiac biomarkers in cancer-therapy-related cardiotoxicity, galectin-3 and MPO are currently under investigation for their use in the early detection of cardiotoxicity." (PMID 36551214, 2022).
cancer (continued). "Overexpression of galectin-3 promotes a number of key steps in cancer progression and metastasis, e.g., adhesion, invasion, migration, and angiogenesis, through its interaction with various galactose-terminated cell surface glycans." (PMID 36291660, 2022). "Data from other types of cancers support a model in which the ability of extracellular Galectin-3 and Galectin-1 to bind to cell surface glycoproteins is regulated by the exact composition of the glycan structures attached to client proteins." (PMID 36430839, 2022). "It has been also proposed that LAMP1 facilitates the metastasis of cancers by acting as a ligand for galectin 3 and can increase translocation to the cell membrane." (PMID 35145930, 2022). "Dysregulated galectin-3 has been characterised in the pathogenesis of several diseases, such as heart failure, cancer and pulmonary hypertension." (PMID 36311252, 2022). "These tumoral metabolic processes are affected by proteins, including Galectin-3 (Gal-3), which is extensively involved in cancer development." (PMID 35886983, 2022). "Galectin-3 (Gal-3), up-regulated in brain injury, inflammation, and cancer, has a suggested role in modulating both neurogenesis and gliogenesis in the adult SVZ." (PMID 35359410, 2022). "Galectin-3 (gal-3) is another LAG3 ligand expressed by epithelial, myeloid, and stromal cells, including cancer-associated fibroblasts (CAFs)." (PMID 35345849, 2022). "In prostate cancer, galectin-3 is mainly localized at the cytoplasmic compartment of cancer specimens and its low expression is also related to poor progression of patients." (PMID 36713574, 2022). "In cancer, T antigen serves as a specific ligand of galectin-3, providing a pivotal interaction for metastatic cell adhesion to endothelial cells in several cancer models." (PMID 35428302, 2022). "The homotypic affinity between cancer cells can be attributed to the interaction between galectin-3 and carcinoembryonic antigen expressed on cancer cells." (PMID 36544135, 2022). "Elevated expression of galectin-3 in cancer progression has been observed and found to contribute to cancer growth, invasion, migration, angiogenesis and immunosuppression of TME." (PMID 35927755, 2022). "Galectin 3 is a beta-galactoside-binding protein that is commonly overexpressed in most types of cancer." (PMID 36296562, 2022). "Galectin-3 is a multifunctional protein and is involved in various steps in cancer development, progression, and metastasis by binding to a number of galactose-terminated, N- and O-linked cell surface glycans." (PMID 36291660, 2022). "Although the mechanism of this inhibition of metastasis is still unclear, the linkage of heparin has a significant inhibitory effect on galectin-3-mediated cancer cell metastasis." (PMID 36296562, 2022). "Co-cultures of epithelial and endothelial cells result in increased galectin-3 secretion in cancer cells and the presence of a proteolytically cleaved galectin-3 in the medium." (PMID 35884405, 2022). "The extent, intensity, and immunohistochemical reactivity of epithelial and stromal galectin-3 expression were reduced in the cancer group." (PMID 36578551, 2022). "Galectin-3 (Gal‐3), a member of the β-galactoside binding protein family, is both a prognostic indicator and a potential target for cancer treatment." (PMID 36071472, 2022). "A total of two studies (133 patients) were included in the assessment of pre–post galectin-3 levels in relation to cancer-therapy-related cardiotoxicity with an HR of 1.39 (90% CI 0.97, 1.98) (I2: 0%, p = 0.39)." (PMID 36551214, 2022). "Among the molecular mechanisms accounting for the powerful lymphocyte inhibitory effect of galectin-3 in cancers, this protein modulates the interactions between T cells and antigen-presenting cells." (PMID 34572756, 2021). "We identified galectin-3 on the surface of these cancer cells and proposed a model that the collagen-like domain of galectin-3 interacts with GPVI." (PMID 34322381, 2021).
cancer (continued). "Last, we showed that the GPVI–galectin-3 interaction induces chemoresistance in cancer cells, and Revacept can inhibit this effect." (PMID 34290095, 2021). "Replacing wild-type cancer cells with KO-g3 cells in OTME-Chip identified the key regulatory role of GPVI–galectin-3 interaction in metastasis." (PMID 34290095, 2021). "An established modified citrus pectin (PectaSol®, P-MCP), a dietary polysaccharide, is an established antagonist of galectin-3, a carbohydrate-binding protein involved in cancer pathogenesis." (PMID 34959847, 2021). "In tumors, it was reported that the cancer cells express certain surface adhesion molecules such as N-cadherin, galectin-3 and epithelial cell adhesion molecule (EpCAM), which are responsible for multicellular aggregate formation." (PMID 34070233, 2021). "Patients with poorly differentiated G3 cancer had significantly higher median galectin-3 levels (IIIB, LVSI+, G2-G3, median 22.6 ng/mL) than patients with well-differentiated cancer (IA, LVSI-, G1, median 15.7 ng/mL)." (PMID 33799622, 2021). "Galectin-3, expressed by many cell types especially epithelial and immune cells, is commonly over-expressed in cancer and promotes cancer progression and metastasis by interaction with galactoside-terminated cell surface glycans." (PMID 34223877, 2021). "Galectin-3 controls cellular proliferation and apoptosis in normal cells as well as malignant transformation and metastasis in cancer cells." (PMID 34208730, 2021). "It is an orally administered competitive inhibitor of galectin-3 (Gal-3), a carbohydrate-binding protein involved in cancer pathogenesis." (PMID 34959847, 2021). "Increased circulation of galectin-3 is frequently seen in cancer patients including colorectal, breast, lung, pancreatic cancer and melanoma." (PMID 34223877, 2021). "Nevertheless, the impact of galectin-3 inhibition seems to apply to other cancers, including hot cancer." (PMID 34572756, 2021). "Recently, Wang studied the regulation by Galectin-3 (Gal-3), a carbohydrate-binding protein related to cell migration, cell adhesion, and cell–cell interaction in cancer cells." (PMID 35054401, 2021). "Galectin-3 has been extensively studied in cancer biology and is considered a “pro-angiogenic” molecule." (PMID 34616740, 2021). "LGALS3 expression varies according to cancer staging and the degree of differentiation of the adenocarcinoma." (PMID 34290978, 2021). "LGALS3 mRNA levels were higher in early stage colorectal cancers (58% in stage I) compared to advanced cancers (50% in stage IV)." (PMID 34290978, 2021). "It is believed that galectin-3 (gal-3) inhibition is responsible for the anti-cancer actions of low molecular weight pectins." (PMID 33800895, 2021). "Thirdly, we observed an increased expression of several immune checkpoints, including PD-L1 (CD274), PD-L2 (PDCD1LG2), CD73 (NT5E), and galectin-3 (LGALS3) in the nutlin-3 resistant cancer cells." (PMID 35582010, 2021). "In tumors, multi-cancer-cellular aggregation are usually ascribed to surface adhesion molecules (eg., epithelial cell adhesion molecule (EpCAM) and galectin-3) expressed on the surface of cancer cell membranes with homologous adhesion domains." (PMID 34952587, 2021). "The expression of galectin-3 and galectin-9 on PC-3 cells that are proteins binding to β-galactoside sugars to provide potential biomarkers and therapeutic targets in particular cancer should be checked in the future." (PMID 33807287, 2021). "The chimeric galectin-3, which consists of monomers that can be arranged in different spatial configurations, was also elevated in all cancers tested." (PMID 34638303, 2021). "In one study, the IHC staining of CRC tissue (n=61) and normal adjacent tissue (n=23) samples showed significantly higher LGALS3 expression in cancer tissue (62.5%) versus normal cancer-adjacent tissue (13.0%)." (PMID 34290978, 2021). "The sensitivity of galectin-3 for diagnosis of carcinomas (FVPTC and FC) is 75% and the specificity is 90.5%." (PMID 34711014, 2021).
cancer (continued). "By binding to Galectin-3, pectins block the inhibition of T-cell mediated immunity against cancer cells and can therefore be used in anticancer therapy." (PMID 32908213, 2020). "Galectin-3 is considered a cancer biomarker and bioindicator of fibrosis and cardiac remodeling and, therefore, it is desirable to develop convenient methods for its detection." (PMID 31991555, 2020). "Galectin-3 has an important function in cancer development and in inflammatory and immune responses." (PMID 33150039, 2020). "A significantly higher median of galectin 3 levels was also observed in patients with low-differentiated G3 cancer as compared to the medial of galectin 3 levels in patients with well-differentiated cancer." (PMID 32859099, 2020). "Galectin 3 is a natural ligand for mucin 1; after binding, it triggers the endothelial growth factor and epidermal pathways opening up the possibilities for cancer spread." (PMID 32859099, 2020). "Pectin is rich in β-galactose units, which can bind specifically to the galectin-3 adhesive molecule, which is commonly overexpressed in various types of cancers." (PMID 32235765, 2020). "No data are available from any studies for any comparison of serum galectin 3 levels in this type of cancer." (PMID 32859099, 2020). "Galectin-3 (Gal-3) is a glycan-binding lectin with a debated role in cancer progression due to its various functions and patterns of expression." (PMID 32231800, 2020). "Though galectin-1 and galectin-3 are also immunomodulators, galectin-9 is widely considered to be the strongest immune modulator related to cancer." (PMID 32033052, 2020). "Galectin 3 levels were significantly higher for tumors of higher stage as well as for cancers which had spread into the lymph nodes, possibly indicating that galectin 3 plays a role in the spread of cancer." (PMID 32859099, 2020). "Galectin-3 (Gal-3), which is a member of the galectin protein family, promotes inflammatory responses and enhances the homotypic aggregation of cancer cells." (PMID 31127200, 2020). "One of them is galectin-3, a β-galactoside-binding protein that regulates cell–cell and cell–ECM interactions and is highly associated with tumorigenesis and cancer progression." (PMID 32079295, 2020). "Galectin-3 is often low in slow-growing tumors, but high levels of galectin-3 indicate more aggressive forms of cancer with higher rates of metastasis and poor outcomes." (PMID 32033052, 2020). "Pectin can serve as a self-targeting agent to cancer cells via β-galactose units, which can bind specifically to galectin-3 adhesive molecules." (PMID 32235765, 2020). "The lactose was chosen in order to bind Galectin-3 (Gal-3), a member of galectin family strictly involved in cancer progression." (PMID 33182755, 2020). "Recent observations have identified high affinity binding between the common cancer antigen Gal(β1–3)GalNAc(α1-O-Ser/Thr (Thomsen–Friedenreich antigen,) and Galectin-3, which appears to enhance metastatic behaviors." (PMID 32486344, 2020). "The concentration of galectin-3 is also increased up to fivefold in the sera of cancer patients, including those with the early stages of cancer." (PMID 32280709, 2020). "Prominent examples are galectin-3 (Gal-3) and galectin-3 binding protein (Gal-3bp), which are actively involved in cancer metastasis." (PMID 31700673, 2019). "Galectin-3 is a member of the lectin family and plays a role in cell-to-cell adhesion, cell-matrix interaction, and cancer metastasis." (PMID 31252633, 2019). "The NWGR anti-death motif suppresses apoptosis of cancer cells induced by chemotherapeutic agents, such as cisplatin, and thus, galectin-3 plays an important role in the resistance to anticancer drugs." (PMID 30585294, 2019). "Galectin-3 protects cancer cells from different types of apoptosis by acting on mitochondrial pathways." (PMID 31683865, 2019). "There are also several lines of evidence pointing to the relevance of galectin-3 for cancer cell migration and invasion." (PMID 30765738, 2019).